MACC1 (MET transcriptional regulator MACC1)
Diseases named in the same sentence as MACC1 in open-access papers (continued):
Sharing a sentence is not in itself a finding about the gene and the disease.
tumor (continued). "Accordingly, MACC1 expressing CRC tumor lesions and metastases revealed an increased uptake of 18F-FDG and 18F-glutamate in our in vivo mouse experiments." (PMID 33652667, 2021). "The manuscript addressed on the regulatory relationship and tumor prognostic value of transcription factors (TFs) MACC1 and transmembrane protein SPINT1." (PMID 33751856, 2021). "If MACC1 is expressed by the tumor cells, we found ERK activation increased and prolonged after stimulation." (PMID 34247190, 2021). "MACC1 expression levels correlate with tumor formation, progression, metastasis, and patient survival." (PMID 34247190, 2021). "MACC1 was established as a key player and biomarker in tumor progression first in CRC, then across multiple tumor entities." (PMID 33731131, 2021). "Remarkably, tumor growth and metastasis in mice exclusively attributed to ectopic MACC1 overexpression were restricted by AZD6244 and GSK1120212." (PMID 34247190, 2021). "The expression of GLUT-1 and MACC1 was quantified by immunohistochemical, and the correlation between metabolism parameters and tumor biomarkers were analyzed." (PMID 33750337, 2021). "A high level of GLUT-1 and MACC1 expression show a predict capacity for stratified tumor pathological factors (T status and differentiated degree)." (PMID 33750337, 2021). "IGFBP2 is a known factor for malignancy and aggressiveness in different tumor entities regarded as a biomarker, which seems to be in line with the biomarker function of MACC1." (PMID 34830078, 2021). "MACC1 transcripts in CRC patient’s tumor tissue and blood predict metastasis formation and patient survival, thereby also allowing the early identification of high-risk patients [4, 6, 8–14,]." (PMID 34247190, 2021). "LncRNA DEAD/H box protein 11 antisense RNA 1 (DDX11-AS1) directly binds to tumor-suppressive miR-195-5p, thus allowing MACC1, a key regulator of the hepatocyte growth factor-HGF receptor (HGFR) pathway, to be overexpressed in HCC." (PMID 33652661, 2021). "MACC1 induces cell proliferation, dissemination, migration, and invasion in cell culture, as well as tumor progression and metastasis in mouse models." (PMID 34247190, 2021). "It has been found that MACC1 expression in tumor lesions of CRC patients is significantly increased relative to their non-tumor adjacent tissues." (PMID 33712897, 2021). "Here we report for the first time the ability of clinically relevant MEK1 inhibitors to restrict MACC1-induced cell migration, tumor growth, and most importantly, metastasis in mice." (PMID 34247190, 2021). "MACC1 (Metastasis Associated in Colon Cancer 1) is found to regulate the hepatocyte growth factor (HGF)/Met signal pathway, and plays an important role in tumor proliferation, angiogenesis, and metastasis." (PMID 34072650, 2021). "Univariate analyses revealed that MACC1, E-cadherin, and vimentin levels along with T and N tumor classifications and cancer staging are significant prognostic factors of NPC (P<0.05)." (PMID 33854976, 2021). "In this study, we retrospectively assessed the feasibility of multiple radio-parameters derived from FDG in predicting tumor stages as well as determine the correlation between GLUT-1/MACC1 and TNM stage and tumor glucose metabolism of CRC." (PMID 33750337, 2021). "MET transcriptional regulator (MACC1) is a transcription factor involved in tumor metastasis through the HGF/c-MET/MAPK axis." (PMID 33827418, 2021). "In summary, MACC1 tyrosine phosphorylation is decisive for switching from tumor growth to motility and metastasis." (PMID 34247190, 2021). "We also found that the expression of Ki-67, cyclin D2, and cyclin A was markedly reduced in tumor tissues from MACC1-depleted groups than in those from the controls." (PMID 33425885, 2020). "Several studies have also indicated that MACC1 influences tumor angiogenesis via a series of complicated pathways." (PMID 33425885, 2020).
tumor (continued). "Clinically it was shown that MACC1 expression promotes tumor progression and metastasis formation in more than 20 different solid tumor entities, including CRC." (PMID 32756469, 2020). "Previous studies performed in GBM and other tumor types found a MACC1 dependent regulation of PI3K and c-Met." (PMID 32503676, 2020). "Combined, the in vivo results showed that MACC1 is involved in the regulation of OS tumor growth via the MACC1/HGF/c-Met signaling axis and the regulation of angiogenesis." (PMID 33425885, 2020). "Our study showed a significant rise in the serum MACC-1 levels with the increasing tumor size, grade and TNM stage." (PMID 33400729, 2020). "In the present study, we investigated the impact of the natural product saffron on the tumor-promoting impact of MACC1." (PMID 32756469, 2020). "We and other groups have shown that MACC1 expression levels are increased especially in tumor tissue of patients with poor outcome." (PMID 32670264, 2020). "Immunoblot assays confirmed the effective downregulation of MACC1 expression in tumor tissues from the MACC1-depleted groups." (PMID 33425885, 2020). "To further validate if MACC1 overexpression alters cell-cell interactions we analyzed 3D tumor aggregation to proof the significance of MACC1 overexpression in our system." (PMID 32503676, 2020). "To examine the roles of MACC1 in tumor progression, we constructed a BALB/C nude xenograft mouse model in which mice were transplanted with shMACC1‐NC and shMACC1 and vector‐NC and MACC1 stably transfected cell lines." (PMID 31557409, 2019). "Log-rank Mantel-Cox analysis of stratified variables in survival by tumor MACC1 status (median = 0.95) in CRC patients*." (PMID 30805302, 2019). "MACC1 induces fundamental processes like proliferation, migration, and invasiveness resulting in tumor progression and metastasis in xenografted and transgenic mouse models." (PMID 30927479, 2019). "The proliferative, migratory, and tumor-formation abilities of GBM cells were significantly boosted by MACC1 expression." (PMID 31200581, 2019). "In conclusion, we provided the evidence that tumor lesion MACC1 status is a clinical prognostic biomarker for patients with CRC and that it is also an improved prognostic significance for distinct stratified clinical parameters." (PMID 30805302, 2019). "In this study, we found that MACC1, c‐Met, and PDL1 expressions were significantly higher in GC tumor tissues, and their expression levels were significantly associated with tumor grades." (PMID 31557409, 2019). "Compared with those from the vector‐NC group, the expression of IFN‐γ and IL‐2 was decreased and the expression of IL‐10 was increased in the tumor tissue samples from the MACC1 group; this difference was significant (P < .05)." (PMID 31557409, 2019). "Enhanced MACC1 expression has been reported to be significantly related to tumor metastasis and worse disease outcome, and to be an early risk factor for cancer patients." (PMID 30805302, 2019). "In the current study, we evaluated the prognostic significance of tumor lesion MACC1 expression in 503 CRC patients." (PMID 30805302, 2019). "We showed that MACC1 overexpression increases the proliferative, migratory, and tumor-formation abilities of GBM cells in vitro and in organotypic hippocampal slice cultures of mice." (PMID 31200581, 2019). "After 4 weeks, tumors from the shMACC1 group were significantly smaller than those from mice transfected with shMACC1‐NC, and silencing of MACC1 significantly reduced xenograft tumor volume (P < .05) and tumor weight (P < .05)." (PMID 31557409, 2019). "In a mouse model, Chanti-MACC1 leads to diminished tumor growth, reduced metastasis, and promotes the long-term survival of the animals." (PMID 31200581, 2019). "Authors further addressed that MACC1 overexpression favors tumor growth and promotes tumor metastasis in an athymic mice model." (PMID 30805302, 2019).
tumor (continued). "MACC1 is also reported to not only promote tumor cell proliferation, invasion, and dissemination by inducing epithelial-mesenchymal transition (EMT) in vitro but also to induce tumor cell growth, invasion, and metastasis in vivo." (PMID 30021598, 2018). "MACC1 acts as a key driver in tumor progression towards more advanced tumor stages and metastasis formation." (PMID 28570591, 2017). "Our results demonstrate that lovastatin inhibits MACC1 expression at the site of the primary tumor in the spleen and intervenes with metastasis formation to the liver in the CRC xenografted SCID-beige mouse model." (PMID 28570591, 2017). "Apart from its crucial role in CRC progression and metastasis, recent studies indicate the relevance of MACC1 in tumor progression and metastasis of several other solid tumor types." (PMID 28570591, 2017). "MACC1 knockdown rescued the tumor-promoting effect of miR-590-3p down-regulation on the cell viability of GSCs." (PMID 28348518, 2017). "We also found MACC1 overexpression to be positively related to tumor grade, LNM, implantation, and FIGO stage." (PMID 28253891, 2017). "We found that MACC1 down-regulation rescued the tumor-promoting effect of miR-590-3p low-expression on the cell viability, migration, invasion and autophagy of GSCs." (PMID 28348518, 2017). "MACC1 was shown to induce migration, invasion, and proliferation in cell culture, as well as tumor progression and formation of metastases in xenografted and genetically engineered mouse models." (PMID 28570591, 2017). "MACC1 knockdown rescued the tumor-promoting effect of miR-590-3p down-regulation on the migration and invasion of GSCs." (PMID 28348518, 2017). "MACC1 knockdown rescued the tumor-promoting effect of miR-590-3p down-regulation on the expression of autophagy related genes of GSCs." (PMID 28348518, 2017). "It was revealed that high MACC1 expression was significantly correlated with tumor size (P = 0.000), lymph node metastasis (P = 0.039) and late clinical stage (P = 0.000)." (PMID 27911852, 2017). "Although no significant inverse correlation was found, miR-218 was significantly downregulated and MACC1 significantly upregulated in tumor tissues compared to the normal mucosa." (PMID 27462788, 2016). "Investigation of association between MACC1 and KAI1 protein levels with clinicopathological parameters of GAC indicated association between the expression of each with tumor grade, lymph node metastasis, invasive depth, and TNM stages." (PMID 27793161, 2016). "S100A4 as Wnt/β-catenin target gene as well as MACC1 were independently found at the tumor invasion front in CRC patients." (PMID 27331819, 2016). "Since its discovery, numerous studies in a variety of different solid cancer entities such as CRC, gastric and hepatocellular carcinoma, demonstrated that MACC1 serves as a prognostic biomarker for patient tumor progression and metastasis." (PMID 27462788, 2016). "miR-218 induced changes can be in part rescued by MACC1 overexpression which indicates MACC1 as novel target and mediator of the tumor suppressor miR-218 function." (PMID 27462788, 2016). "Taken together, these results revealed that MACC1 accelerated tumor growth and induced endothelium-dependent angiogenesis of GC." (PMID 27280289, 2016). "In this study, we report that the tumor suppressor miR-218 post-transcriptionally downregulates MACC1." (PMID 27462788, 2016). "Very recently, Barbazan and colleagues reported the prognostic relevance of a S100A4/MACC1 cluster in circulating tumor cells for progression-free and overall survival of patients with metastatic CRC." (PMID 27331819, 2016). "High expression of MACC1 induced proliferation, migration and invasion of cancer cell lines and induced tumor growth and metastasis formation in mice." (PMID 27462788, 2016).
tumor (continued). "Subcutaneous, orthotopic, and intrasplenic transplantation of MACC1-expressing tumor cells induced tumor growth and metastasis in mice, shRNA acting on MACC1 or MACC1 targets decreased metastases." (PMID 27439755, 2016). "Taken together, these data demonstrate that miR-218 is inhibiting, at least in part, the MACC1-mediated tumor progressive events." (PMID 27462788, 2016). "Induced MACC1 expression positively and miR-218 expression negatively mitigate the cancer stem cell functions, which are responsible for the tumor formation, growth and metastasis and resistance to chemotherapy." (PMID 27462788, 2016). "Consistent with the critical role of VEGF-A in angiogenesis, the present study validated that the expression of VEGF-A and MVD, as well as tumor growth were significantly increased in MACC1 overexpression GC cells." (PMID 27280289, 2016). "Based on many AKT and its regulators and positive feedback phenomenon in tumor cells, it demonstrates a probable positive regulatory feedback loop between MACC1 and the PI3K/AKT signaling pathway, which needs to be testified and investigated deeply." (PMID 27581375, 2016). "Previously, we found that MACC1 contributed to poor prognosis of GC by promoting tumor cells proliferation and invasion as well as epithelial-to-mesenchymal transition." (PMID 27581375, 2016). "Expression of MACC1 correlates to tumor formation, metastases and patient survival, determined in cryo and formalin fixed paraffin embedded normal, tumor and metastatic tissues from retrospective and prospective studies." (PMID 27439755, 2016). "Ectopic expression of MACC1 promoted tumor proliferation, significantly upregulated TWIST1 expression in vivo, and induced vascular tube-like formation in vitro." (PMID 27280289, 2016). "We also investigated the apoptosis of tumor cells in xenografts, which showed that trastuzumab induced cell apoptosis when MACC1 was downregulated." (PMID 27581375, 2016). "miR-218 and MACC1 expression were significantly down- or upregulated respectively in a cohort of CRC tumor specimens." (PMID 27462788, 2016). "In consistence with this, strong MACC1 expression at the invasive front correlated with a high grade tumor budding phenotype (p = 0.0006)." (PMID 25884643, 2015). "We performed geographic MACC1 expression analysis in tumor center, invasive front and tumor buds on whole tissue sections of 187 well-characterized CRCs by immunohistochemistry." (PMID 25884643, 2015). "Remarkably, MACC1 levels consistently correlated with tumor progression, development of metastasis and patient survival in this broad range of solid tumor types, making MACC1 a decisive driver for disease progression." (PMID 25884643, 2015). "We demonstrate that MACC1 is variably expressed in normal mucosa, tumor center, invasive front and tumor buds." (PMID 25884643, 2015). "MACC1 expression at the tumor front was strongly predictive for the formation of distant metastasis (p = 0.0223)." (PMID 25884643, 2015). "In CRC patients, MACC1 is a tumor stage-independent predictor for metastasis and survival, and allows early identification of high-risk cases." (PMID 25884643, 2015). "In the current study we perform a geographic analysis of MACC1 expression in CRC with a particular focus on EMT-like cancer cells in the tumor microenvironment, also called tumor buds." (PMID 25884643, 2015). "Taken together, we report for the first time the differential expression of MACC1 in CRC with increasing levels from tumor center to invasion front." (PMID 25884643, 2015). "Aim of this study is therefore to evaluate the geographic expression pattern of MACC1 protein in the tumor center, the invasion front and in tumor buds of clinical CRC samples." (PMID 25884643, 2015). "A higher proportion of MACC1 positive tumor buds was detected in patients with more advanced T-stage (p < 0.0001), higher overall TNM-stage (p = 0.0004) and presence of nodal metastasis (p = 0.0453)." (PMID 25884643, 2015).
tumor (continued). "MACC1 overexpression in tumor budding cells themselves provides further evidence of their biological aggressiveness and likens these cells to EMT-like cancer cells." (PMID 25884643, 2015). "MACC1 staining at the tumor front was seen in aggressive tumors with more advanced pT-stage (p = 0.0005), presence of lymphatic (p = 0.002) and venous (p = 0.0125) invasion as well as frequent nodal metastasis (p = 0.0001)." (PMID 25884643, 2015). "MACC1 mRNA expression was significantly different between tumor and inflammatory tissues (Mann–Whitney U test with a Bonferroni correction; p < 0.05)." (PMID 24934327, 2015). "As death from CRC is predominantly determined by metastatic dissemination, the prognostic impact of MACC1 in this geographic area further corroborates the exceptional importance of the tumor microenvironment for determining prognosis." (PMID 25884643, 2015). "MACC1 is an important pro-metastatic factor that showed significant overexpression following treatment with tumor DNA." (PMID 26133168, 2015). "In tumor tissue, a gradient of MACC1 expression from the tumor center to the invasive front was identified (p = 0.0012)." (PMID 25884643, 2015). "We found that the level of MACC1 mRNA expression differs between primary tumor tissues and inflammatory tissues (p < 0.05, Kruskal–Wallis test)." (PMID 24934327, 2015). "At the invasive front, MACC1 expression predicts best aggressive clinicopathological features, tumor budding, metastasis formation and poor survival outcome." (PMID 25884643, 2015). "Further, MACC1 expression in the tumor center was highly correlated with presence of high-grade tumor budding." (PMID 25884643, 2015). "At the invasive front, MACC1 expression best predicts aggressive clinicopathological features, tumor budding, and metastasis formation." (PMID 25884643, 2015). "MACC1 positivity in the tumor center further predicted aggressive tumor growth with presence of lymphatic invasion (p = 0.0373), venous invasion (p = 0.0352) and frequent metastasis to loco regional lymph nodes (p = 0.0018)." (PMID 25884643, 2015). "MACC1 expression at the invasion front was identified as the best predictor for aggressive clinicopathological features, tumor budding, metastasis formation and poor survival outcome." (PMID 25884643, 2015). "Established as a novel prognostic indicator for metastasis in a broad range of solid tumors, MACC1 has also been proposed to be a target candidate for the development of therapeutic strategies for the intervention with tumor progression and metastasis." (PMID 24949951, 2014). "Tumor with MACC1 over-expression group exhibited a rapid increase (approximately 12-fold) in tumor volume over 21 days." (PMID 25003996, 2014). "Noticeably, MACC1 demonstrated increased abundance in late stage tumor tissues such as TNM stages III–IV, when compared with that in the early stage and the difference was statistically significant (p<0.05)." (PMID 24949951, 2014). "Patients with values >1 (MACC1 expression level of tumor tissue greater than that of the corresponding normal tissue) were assigned to the high-expression group and patients with values <1 were assigned to the low-expression group." (PMID 25295116, 2014). "MACC1 expression was calculated by normalising it to GAPDH expression for each tumor or normal tissue sample." (PMID 25295116, 2014). "Concomitantly, the average final tumor weight in MACC1-transfected group (0.59 g) was significantly more than that in empty vector control group (0.08g) upon termination of the experiment (p<0.001)." (PMID 25003996, 2014). "MACC1 expression in the primary tumor and in plasma of CC patients was shown to be an independent risk factor for metastasis." (PMID 23594791, 2013). "MACC1, a novel regulator of tumor growth and metastasis, has recently been indicated as a potential prognostic factor for metastatic disease in HCC, lung adenocarcinoma, gastric carcinoma and colorectal cancer." (PMID 23717574, 2013).